ZFPM2-AS1 (ZFPM2 antisense RNA 1)
Synonyms: SCAT3
Gene: Long non-coding RNA gene on chromosome 8 (105,546,089 to 106,060,524, reverse strand). Ensembl gene ENSG00000251003.
Diseases named in the same sentence as ZFPM2-AS1 in open-access papers:
ZFPM2-AS1 is named in the same sentence as 5 diseases in open-access papers, as found by Europe PMC text mining. Sharing a sentence is not in itself a finding about the gene and the disease. The quoted sentences say what the papers report.
gastric cancer (2 papers, 2020 to 2021). A primary or metastatic malignant neoplasm involving the stomach. "Recently, a newly identified lncRNA, ZFPM2 antisense RNA 1 (ZFPM2-AS1), was reported to serve as an oncogene in gastric cancer." (PMID 33414427, 2021).
esophageal squamous cell carcinoma (1 paper, 2020). Esophageal squamous cell carcinoma (ESCC) is a type of esophageal carcinoma (EC) that can affect any part of the esophagus, but is usually located in the upper or middle third. "LncRNA ZFPM2 antisense RNA 1 (ZFPM2-AS1) has been identified as a tumor facilitator in some cancers; nevertheless, its functional significance and regulatory mechanism remain greatly unclear in esophageal squamous cell carcinoma (ESCC)." (PMID 32065218, 2020).
ZFPM2-AS1 also shares sentences with these, for which no sentence is quoted: cancer (2 papers); tumor (2); renal cell cancer (1).